NLRP3 (NLR family pyrin domain containing 3)
Diseases named in the same sentence as NLRP3 in open-access papers (continued):
Sharing a sentence is not in itself a finding about the gene and the disease.
cancer (continued). "Assessment of the degree of NLRP3 activation may be valuable in the future in patients like ours with cancer and numerous cardiac disorders, especially when considering the use of potentially cardiotoxic treatment." (PMID 38248011, 2024). "Also in cancer, several points of evidence have shown the anti-tumorigenic and pro-tumorigenic effects of NLRP3." (PMID 39684769, 2024). "The NLRP3 inflammasome and Wnt signaling pathways affect pyroptosis and cell differentiation/apoptosis, respectively, and are potential targets for regulating colon inflammation-cancer transformation." (PMID 38650627, 2024). "Similarly, 3,4-methylenedioxy-β-nitrophenylethylene (MNS), as a particular NLRP3 inflammasome inhibitor, can repress the expression of NLRP3 inflammasome in cell lines, and NLRP3 inhibition can reduce the proliferation and movement of cancer cells." (PMID 38182564, 2024). "However, the NLRP3 inflammasome can also play a role in suppressing cancer through mechanisms related to immune surveillance." (PMID 39769450, 2024). "Unlike other receptor proteins, NLRP3 is highly sensitive to various non-pathogenic factors both environmental and endogenous which can trigger abnormal NLRP3 inflammasome activation, implicated in complex pathologies like IBD, neurodegenerative diseases, and cancer." (PMID 38455052, 2024). "Combination of the NLRP3 dual effect for cancer, colchicine modulates NLRP3 effect for cancer, duration of drug effect and detection bias could play a role for contributing to these results." (PMID 38649928, 2024). "The abnormal activation of the NLRP3 inflammasome, which may promote cancer occurrence, has spurred extensive clinical research on the development of NLRP3 inflammasome inhibitors." (PMID 38317229, 2024). "Our previous study showed that, after NLRP3 activation, cancer cells with a low NLRP3 expression capacity could reduce cell growth and migratory features." (PMID 36902278, 2023). "Role of NLRP3 inflammasome activation or suppression in cancer development." (PMID 37081882, 2023). "In fact, the role of NLRP3 inflammasome in cancer is complex and context-dependent." (PMID 37715239, 2023). "Previous studies have shown that both TLR4 and NLRP3 are upregulated in many human cancers." (PMID 37701157, 2023). "In the last few years, research into NLRP3 regulation by miRNAs has demonstrated great potential in the treatment of several diseases, including inflammatory diseases, autoimmune disorders, and cancers." (PMID 37681916, 2023). "The NLRP3 inflammasome plays dual roles in the pathogenesis of cancers." (PMID 37047097, 2023). "Therefore, the NLRP3 inflammasome has complex and context-dependent effects on cancer development and progression." (PMID 37715239, 2023). "However, the mechanistic action of RRx-001 in inhibiting the NLRP3 inflammasome in cancer is unclear." (PMID 36920652, 2023). "These discrepancies may reflect the different roles of IL-1β/IL-18 and NLRP3 inflammasome in different cancer types or stages." (PMID 37715239, 2023). "The investigation of the NLRP3 inflammasome complex is a new horizon to explore, and inhibiting IL-1β or NLRP3 could be a helpful cancer-related therapeutic strategy to improve the existing protocols." (PMID 36902299, 2023). "Interestingly, a recent bioinformatic analysis also reported decreased NLRP3 expression in a pan-cancer analysis including NSCLC." (PMID 36746533, 2023). "It has been reported that NLRP3 inflammasome plays a dual role in cancer." (PMID 37153780, 2023). "However, activation of the NLRP3 inflammasome promotes the release of IL-1β, which not only creates a pro-inflammatory environment but also has profound effects on cancer cell proliferation, migration, and metastasis." (PMID 36920652, 2023).
cancer (continued). "The goal of this paper is to review new insights on the effects of the NLRP3 inflammasome activation in the complex mechanisms of crosstalk between different organs, for a better understanding of the role of chronic inflammation in cancer pathogenesis." (PMID 37715239, 2023). "At present, there are few studies on the role of NLRP3 inflammasome in cancer by regulating NK." (PMID 37153780, 2023). "In addition, inhibition of NLRP3 inflammasome activity using MCC950 or dampening the downstream effect of IL-1β prevented the proliferation increase in cancer cells." (PMID 37749707, 2023). "As drug resistance strictly limits the therapeutic efficacy of chemotherapy and seriously harms patients' health and life, increasing attention has been paid to whether NLRP3 can also regulate the malignant processes against drug resistance in cancer." (PMID 37304662, 2023). "Here, we report that NLRP3 expression is down-regulated in human cancers." (PMID 36746533, 2023). "The NLRP3 is an intracellular sensor that detects a broad range of microbial motifs, leading to the formation and activation of the NLRP3 inflammasome, which is involved in the regulation of various diseases, from autoimmune disorders to cancer, representing a promising transversal target." (PMID 37986089, 2023). "The Gasdermin (GSDM) family member genes NLRP3, NLRC4, NLRP1, AIM2, IL-1β, and IL-18 are linked to TIME, and the immunosuppressive microenvironment can be overcome by targeted pyroptosis therapy in cancers." (PMID 36882663, 2023). "This suggests the NLRP3 inflammasome as a novel cancer immunetherapy target." (PMID 36711732, 2023). "Therefore, based on mouse studies, the NLRP3 inflammasome has become a promising target for cancer treatment, and successfully blocks the progression of several types of cancer." (PMID 36672229, 2023). "Pyroptosis also helps to induce progressive NLRP3 inflammasome activation by releasing DAMPs, but the lytic and immunogenic nature of pyroptosis ensures to demising cancer cells and containing cancer progression by immune resistance effect." (PMID 38031068, 2023). "The existing evidence suggested that NLRP3 inflammasome might be an effective target for the adjuvant chemotherapy of multiple types of cancer." (PMID 37304662, 2023). "The most well-studied inflammasome involved in cancer development is the NLRP3." (PMID 37715239, 2023). "Whereas its role in the context of cancer has been mostly explored in the immune compartment, whether NLRP3 exerts functions unrelated to immunity in cancer development remains unexplored." (PMID 36746533, 2023). "Moossavi and colleagues recently summarized the known role of NLRP3 inflammasome in cancer." (PMID 37819510, 2023). "Besides NLRP3 inhibition, activity of RRx-001 in cancer depends on the convergence of multiple mechanisms, including macrophage polarization, CD47 antagonism, vascular normalization, and epigenetic modification." (PMID 36920652, 2023). "Therefore, the relationship between NLRP3 inflammasome and apoptosis, especially in cancer, needs further study." (PMID 37153780, 2023). "Low‐dose diosbulbin‐B (DB) could inhibit properties of cancer stem cells and induce PD‐L1 depletion to activate NLRP3‐dependent pyroptosis, which effetely sensitize cisplatin‐resistant GC cells." (PMID 37125240, 2023). "Besides, another study elaborated the molecular mechanism by which the NLRP3 inflammasome initiated cancer cell death in HCC." (PMID 37051536, 2023). "However, in subsequent chapters describing the application of pyroptosis in cancer, it was found that many drugs inhibit cancer by activating NLRP3 to initiate pyroptosis." (PMID 37752941, 2023). "In addition, the secretion of IL-1β is tightly regulated by NLRP3 inflammasome and targeting the inflammasome has emerged as a new therapeutic strategy for cancer." (PMID 37020461, 2023).
cancer (continued). "Our findings are consistent with preclinical data showing that NLRP3 inhibitors augment the efficacy of PD-1/L1 inhibitors and suggest that combination therapy could be beneficial for the treatment of these cancers." (PMID 37242422, 2023). "NLRP3 inflammasome-related genes have been proven to be dysregulated in various cancers and these alterations may either lead to favorable or detrimental results." (PMID 38031951, 2023). "Therefore, to decipher anti-NLRP3-based cancer drugs, it is important to unravel the molecular mechanisms that promote immunocompromised conditions and initiate autophagy, promoting cancer cell survival." (PMID 37893079, 2023). "Moreover, the pro-cancer effects of TC are widely accepted to be mediated through multiple mechanisms, including TC-induced NLRP3 inflammasome activation." (PMID 36860687, 2023). "It should be noted that ODZ is a STAT3 inhibitor and its inhibitory activity on both STAT3 and NLRP3 inflammasome might be beneficial to cancer treatment." (PMID 37047051, 2023). "Therefore, it is important to distinguish between the effects of IL-1β/IL-18 and the effects of NLRP3 inflammasome in cancer biology." (PMID 37715239, 2023). "Thus, attributed to the dual role in different types of malignant tumor, NLRP3 inflammasome was regarded as a double-edged sword in tumorigenesis." (PMID 37304662, 2023). "In addition, NLRP3 contributed to immunosuppression and promoted the expression of PD-L1 in various cancers including BC." (PMID 37762557, 2023). "Therefore, more research is needed to understand the mechanisms and implications of NLRP3 inflammasome activation in different cancer settings, and we focus on the role of NLRP3 inflammasome in cancer in the present review." (PMID 37715239, 2023). "However, the role of NLRP3 complex in cancer remains controversial since it can both induce or suppress cancer growth." (PMID 38031951, 2023). "Here, we list some inhibitors of NLRP3 that can influence cancer progression." (PMID 37081882, 2023). "In addition to activating the NLRP3 inflammasome to induce cancer cell pyroptosis, ROS can also induce pyroptosis through the caspase-3/GSDME pathway." (PMID 36612023, 2022). "Chronic inflammation is led by the release of pro-inflammatory cytokines; however, while NLRP3 is an important mediator in inflammation, reports show that NLRP3 can have both a destructive and protective role in different types of cancer, making NLRP3’s role in cancer complex." (PMID 35754962, 2022). "Activation of the NLRP3 inflammasome leads to the release of the proinflammatory cytokines IL-1β and IL-18, which may contribute to cancer development." (PMID 35707534, 2022). "Also known as a member of the inflammasome complex, the pyrin domain-harboring the protein 3 (NLRP3) inflammasome contributes to inflammation, and regulates cancer pathogenesis by modulating immune response, cell death, and proliferation." (PMID 35296025, 2022). "Activation of the NLRP3 inflammasome signaling has the potential to inhibit cancer growth." (PMID 36555392, 2022). "Methylation of GPX4, NLRP3, and CASP5 were associated with better prognosis in majority of cancers." (PMID 36605187, 2022). "TAT-FADD inhibits the initiation of classic NLRP3 inflammasomes and limits the processing and secretion of pro-inflammatory IL-1β, thereby regulating the anti-apoptotic and pro-inflammatory NF-κB signal activation in cancer cells." (PMID 35664309, 2022). "Discussion: Our data suggest that Cf could suppress LPS induced NLRP3, which should be considered when selecting antibiotics for cancer treatment." (PMID 36012769, 2022).
cancer (continued). "In detail, the effects of exosomes on NLRP3 inflammasome activation depend on the origin of exosomes, including inhibition (from plasma, mesenchymal stem cells, and macrophages) and promotion (from cancer cells)." (PMID 35694441, 2022). "Although specific feasible therapy is still underexplored, targeting the NLRP3 inflammasome provides a novel, promising way of treatment and secondary prevention of CVDs and some immune-related diseases, including certain severe cancers." (PMID 36204568, 2022). "In addition, cancer-derived exosomes have been found to promote NLRP3 inflammasome activation in macropahges." (PMID 35694441, 2022). "After exposure of CXCR4+ SW1417 cells to the T22-PE24-H6 nanotoxin for a short time, at 2 or 5 hours, we found in almost all cancer cells a high overexpression of the NLRP3 protein, an inflammatory marker that initiates the signaling cascade that leads to pyroptosis." (PMID 35532120, 2022). "NLRP3 involvement in cancer is currently a very debated topic." (PMID 35530309, 2022). "The exact role of NLRP3 in different types of cancer is multiplex, but therapies that target inflammation may be of value to some diagnoses." (PMID 35754962, 2022). "Indeed, beyond tumorigenic effects, also anti-tumorigenic effects of the NLRP3 inflammasome have been reported depending on the type of cancer." (PMID 36466820, 2022). "The role of NLRP3 inflammasome in cancer is arguable, since there are suggestions of a protective anti‐tumorigenic role but also a pro‐tumorigenic effect, depending of the cancer type." (PMID 36327091, 2022). "This might be explained by the complexicity of NLRP3 in cancer and stresses the need for further preclinical studies." (PMID 36466820, 2022). "Specifically, high expression of NLRP1 was significantly correlated with poor OS in patients with stages 1–3 cancer (p = 0.048, p = 0.004, p = 0.0002), whereas high expression of NLRP3 was only correlated with poor outcome in patients with stage 3 GC (OS, p = 0.0003; FPS, p = 0.021)." (PMID 36541912, 2022). "Second, the results of this study could not serve the explanation of pathophysiological relevance of diverse expression of C5AR1, CLEC4A and NLRP3 in CD3+ T-lymphocyte amount cancer patient and healthy individuals." (PMID 36323738, 2022). "Moreover, the NLRP3 inflammasome was also essential for the adaptive immune responses to anti-cancer." (PMID 36276158, 2022). "However, there is a need for further research into the downregulation of NLRP3 and its effects on cancer." (PMID 35877745, 2022). "Therefore, our data suggest that LPS-Az has an inhibitory effect on NLRP3 in cancer cells with a high capacity for inflammasome activation." (PMID 36012769, 2022). "However, aberrant NLRP3 inflammasome activation has also been shown to drive the progression of many major human diseases, including various types of cancer, as well as metabolic and degenerative disorders." (PMID 35740272, 2022). "This suggests that cancer cell inoculation induced the activation of the NF-κB/NLRP3 inflammatory axis in the spinal cord of BCP rats, which may be a potential target for the treatment of BCP." (PMID 34484316, 2021). "Schematic representation of the several cancer types in which NLRP3 inflammasome is involved." (PMID 34064909, 2021). "The progression of cancer cells could be suppressed by reduced NLRP3 inflammasome and IL-1β expression." (PMID 34747716, 2021). "The NLRP3 inflammasome is the most well-studied inflammasome involved in cancer development." (PMID 34540671, 2021). "The NLRP3 inflammasome complex has attracted considerable attention for its role in the development of several other cancer types, but this role remains unclear and controversial." (PMID 34064909, 2021). "aim of thitudy wasaimed to determine whether activation of NLRP3 inflammasome is positively or negatively correlated with cancer progression and EMT markers in CRC patients." (PMID 34094030, 2021).
cancer (continued). "In addition, extracellular ATP released from damaged tumor cells upon anti-cancer treatment also induces NLRP3 inflammasome activation." (PMID 34684819, 2021). "Though, the controversial role of NLRP3 inflammasome in the carcinogenesis has been debated, increasing evidences emphasize that NLRP3 inflammasome promotes chronic inflammatory response which contributes to cancer initiation, development and progression." (PMID 34211462, 2021). "However, studies that have directly assessed the intrinsic role of NLRP3 in the regulation of cancer have depicted a complex scenario that mainly involves its aberrant expression or function." (PMID 34064909, 2021). "Therefore, we sought to determine the effect of doxycycline on NLRP3 regulation in cancer using an in vitro model." (PMID 34577552, 2021). "Therefore, the fine-tuning of the NLRP3 inflammasome in cancer cells, through a wide range of agents including, such as inhibitors, antagonists and monoclonal antibodies, has been suggested as a viable approach to cancer therapy." (PMID 34064909, 2021). "Berberine inhibited P2X7-mediated NLRP3 inflammasome activation in human TNBC cells, which might provide therapeutic relevance for clinical use since targeting the NLRP3 inflammasome pathway, is suggested to be a potential strategy for cancer immunotherapy." (PMID 34948368, 2021). "Additionally, NFκB is involved in NLRP3 inflammasome activation and its pro-tumorigenic role has been widely described in cancer." (PMID 34211462, 2021). "In addition, a review of the TCGA database also shows an array of cancer types harboring genetic alterations in NLRP3." (PMID 34638239, 2021). "Although there is no direct evidence that oridonin induces anticancer activity by inhibiting the NLRP3 inflammasome, its ability to suppress cell proliferation, migration and invasion has been described in ovarian, breast, osteosarcoma and esophageal cancers." (PMID 34064909, 2021). "Thus, we examined how the expression of NLRP3 in HCC cells affects cancer surveillance by NK cells in a state of a co-culture of both cells." (PMID 34502191, 2021). "However, most studies have disclosed the caspase‐1 as the prominent regulator in various cancers, characterized by the discharge of several pro‐inflammatory elements like released pro‐inflammatory actors like NLRP3 and L‐1β into the cytoplasm." (PMID 34369076, 2021). "In addition to its roles in infection, cardiovascular disease, cancer and Alzheimer’s disease to name but a few, the NLRP3 inflammasome is widely studied in the context of inflammatory and autoimmune diseases." (PMID 33995417, 2021). "NLRP3 inflammasome activation, caspase-1 activation, release of IL-1β and IL-18 pro-inflammatory cytokines and gasdermin D-mediated pyroptotic cell death are important mechanisms involved in inflammation-induced cancer." (PMID 34452150, 2021). "ABRO1 as a scaffold for the interaction between NLRP3 and breast cancer susceptibility gene complex subunit protein 3 (BRCC3), acting synergistically with BRCC3 promotes the inflammatory activation of NLRP3 by regulating the deamination of NLRP3." (PMID 34381452, 2021). "The NLRP3 inflammasome is involved with several inflammatory-based diseases, including cancer." (PMID 33918290, 2021). "Targeting the NLRP3 inflammasome, alone or in combination with chemotherapy, may be a promising potential therapeutic approach in cancers." (PMID 35008212, 2021). "Cell pyroptosis was a type of cell death featured by NLRP3 inflammasome activation and pro-inflammatory cytokines secretion, and induction of pyroptotic cell death was proved to be an effective strategy to eliminate cancer cells." (PMID 33579380, 2021). "The NLRP3 inflammasome contributes to the progression of a range of human cancers." (PMID 34457117, 2021). "Once activated, these NLRP3 inflammasomes may drastically promote cancer angiogenesis, endothelial cell proliferation, and immunosuppressive cell activation via releasing IL-1β and IL-18." (PMID 34588926, 2021).